CD14 (CD14 molecule)
Diseases named in the same sentence as CD14 in open-access papers (continued):
Sharing a sentence is not in itself a finding about the gene and the disease.
COVID-19 (continued). "Quantitative analysis indicated significant increases in IBA-1+ microglia, CD16+ and CD14+ mononuclear cells in COVID-19 patient brains when compared with control brains." (PMID 36609561, 2023). "Cell-cell communication analysis indicated that compared with healthy controls, severe COVID-19 cases had increased intercellular signaling and enhanced communication between CD14 monocytes and CD16 monocytes." (PMID 38022594, 2023). "Mono_CD14 cells were significantly elevated in the COVID-19 severe disease and acute necrotizing encephalopathy groups." (PMID 37848421, 2023). "DGE analysis revealed 11, 9, and 30 genes differentially expressed between patients who survived versus those who succumbed to COVID-19 (log2 fold-change > 0.58) in CD14 monocytes, CD16 monocytes, and cDC2 cells, respectively." (PMID 35169146, 2022). "The relative proportion of macrophages was higher in follicles of COVID-19 samples compared to controls, although the percentages of CD14+CD16- or CD14+CD16+ or CD14loCD16+ macrophages were similar between groups." (PMID 35251032, 2022). "The percentage and counts of immune-suppressive monocytes (mo-MDSCs) identified as CD14+ HLA-DR− monocytes were higher than normal values in severe COVID-19+ patients, independently from the amount of IL-6, IL-1β, IL-17A, TGF-β, TNF-α and IFN-γ." (PMID 35508575, 2022). "Earlier, it has been demonstrated that COVID-19 patients with severe respiratory failure exhibit low HLA-Dr expression on CD14+ monocytes relative to that of mild COVID-19 patients or healthy volunteers." (PMID 35213582, 2022). "Therapeutics targeting CD14 have been studied and are currently being developed, such as the use of a monoclonal anti-CD14 antibody (IC14) for the treatment of severe COVID-19." (PMID 35429403, 2022). "Analysis of monocyte subset frequencies based on CD14 and CD16 expression revealed significantly lower proportions of classical (CD14+ CD16-) monocytes during acute COVID-19." (PMID 35007290, 2022). "DNA samples extracted from CD14 + CD15- monocytes of 48 severe COVID-19 patients and 11 healthy controls were hybridized on MethylationEPIC BeadChip arrays." (PMID 36443794, 2022). "In general, the expression levels of IL17RA gene had significantly positive correlations with COVID-19 severity scores in CD14- positive monocytes (ρ = 0.474 and P = 0.0017) and neutrophils (ρ = 0.488 and P = 0.0016)." (PMID 36481664, 2022). "Here, we examine the phenotype and functionality of the main monocyte population in humans, i.e., classical CD14+ monocytes, in patients with COVID-19 during the acute phase of disease and compare them to those of healthy individuals." (PMID 36572683, 2022). "KMT2E is a gene related to lysine degradation in mono-CD14+ cells and has been shown to be downregulated in severe COVID-19 patients." (PMID 35755819, 2022). "To confirm these gene expression data, we used SCENITHTM31 to metabolically profile CD14+ monocytes from COVID-19 patients and healthy controls ex vivo." (PMID 36572683, 2022). "FACS confirmed the reported increase in immature CD15++/CD24++ neutrophils and the reduction of CD14++/CD16dim classic monocytes during severe COVID-19 (WHO grade > 4), indicative of myeloid exhaustion." (PMID 35998224, 2022). "Here, we examine the function of classical CD14+ monocytes in patients with mild and moderate COVID-19 during the acute phase of infection and in healthy individuals." (PMID 36572683, 2022). "A reduced number of CD14+ monocytes relative to control values was observed in patients with a severe course of COVID-19." (PMID 35632823, 2022). "Representative dot-plots illustrate the comparison of CD14++CD16- classical monocytes expressing IFN-alpha in blood samples treated with polyclonal stimuli from participants who developed mild or severe COVID-19 during the follow-up." (PMID 35860236, 2022).
COVID-19 (continued). "We focused the analysis on CD14+ monocytes and B cells, which show perturbed transcriptomes in COVID-19 patients and are both frontline sensors of infection." (PMID 34969849, 2022). "Individuals recovered from severe and critical COVID-19 had reduced frequencies of plasmacytoid DCs (pDCs) and CD14+ DC3s (Bonferroni-adjusted P-value range 0.00226–3.71 × 10−7)." (PMID 36433939, 2022). "An increase in intermediate CD14+ CD16+ monocytes in patients with different clinical severity of COVID-19 in comparison with healthy individuals has been observed before, but the exact mechanism of this phenomenon has not been elucidated yet." (PMID 35458548, 2022). "To examine the role of macrophages in SARS-CoV-2 infection and COVID-19 pathogenesis, we differentiated primary MDMs from multiple donors by culturing CD14+ monocytes in the presence of human AB-serum and M-CSF for 6 days." (PMID 36279285, 2022). "We further evaluated the transcriptional and epigenomic profiles of CD14+ monocytes from patients who experienced severe COVID-19." (PMID 35380990, 2022). "We noted reduction of the HLA expression for Mon IFI 30, Mon CD14, and Mon HLA in severe groups with Delta lineage when compared with influenza, healthy, or other COVID-19 samples." (PMID 36230912, 2022). "We found that COVID-19 plasma exosomes significantly induced expression of cytokines and chemokines in CD4+ and CD8+ T cells as well as in CD14+ monocytes compared with treatment with plasma exosomes derived from non-COVID-19 patients or healthy donors." (PMID 36526691, 2022). "The detection of the classical CD14+HLA-DR+ monocytes showed a significantly higher percentage in COVID-19 patients (54.7%) compared to HS (26.7%) (p<0.001) but not the VS (51%) (p>0.05)." (PMID 35898494, 2022). "This distinction is important as not only are CD14+ monocytes generally more activated in early COVID-19, as has been described, but here were differentially activated across subjects with variable disease severity." (PMID 35810186, 2022). "T-distributed stochastic neighbor embedding (t-SNE) analysis showed increase of classical (CD14++CD16-) and intermediate (CD14++CD16+) monocytes in COVID-19 patients compared to healthy subjects matched for age and sex." (PMID 35508575, 2022). "There was also a systematic tendency to have larger proportions of CD14 monocytes in COVID-19 (on average 30%–38%) than in controls (on average 15%–23%, p < 0.001 in Combes, p < 0.1 in Wilk, p = 0.2 in Lee data)." (PMID 35991542, 2022). "Whereas in patients with mild COVID-19 an increase in activated classic (CD14+) monocytes is observed, severe COVID-19 is marked by the accumulation of dysfunctional classic monocytes with reduced HLA-DR expression and immature neutrophils." (PMID 35998224, 2022). "To determine the reason for the opposite regulation of PIRAT and LUCAT1 during COVID-19, we compared the influence of both lincRNAs on genes regulated in CD14+ monocytes in patients." (PMID 35998224, 2022). "Flow cytometry analysis confirmed increased intracellular IL-18 and NLRP3 inflammasome expression in CD14+ monocytes of the patient with COVID-19 vaccine-related myopericarditis." (PMID 35251049, 2022). "This was detected in COVID-19 patients with high serum levels of IL-6 and low HLA-DR on their CD14 monocytes, along with a low lymphocyte count." (PMID 35062368, 2022). "Patients with COVID-19 showed an increase in the population of intermediate monocytes with the CD14+CD16+ phenotype, which was generally the highest in patients with a mild disease outcome." (PMID 35632823, 2022). "In the COVID-19 group, coagulation factor XIII A chain (F13A1) and contactin associated protein 2 (CNTNAP2) exhibited the strongest upregulation, with CD14, C1QC, cytochrome C oxidase subunit 7C (COX7C) and (APOE) being increased in the AD group." (PMID 36211330, 2022).
COVID-19 (continued). "A single-cell analysis of PBMCs from COVID-19 found that CD14+ monocytes were significantly increased, while an observed decrease was shown in CD16+ monocytes." (PMID 35573725, 2022). "As a proportion of airway leukocytes, CD14+ monocytes and neutrophils were decreased in post-COVID-19 patients when compared with controls." (PMID 35151371, 2022). "The higher promoter accessibility for LZTFL1 in CD14+ monocytes of deceased patients at admission is in agreement with the observation that increased LZTFL1 expression is detrimental in COVID-19 pathogenesis." (PMID 35648852, 2022). "Vice versa, genes down-regulated in CD14+-monocytes during severe COVID-19 were under significant positive influence by PIRAT, headed by the PU.1-suppressed genes IRF5 and ITGAX." (PMID 35998224, 2022). "In the blood of COVID-19 patients, we observed a greater association of surface expression of TREM-1 with CD14−CD16+ than CD14+ cells." (PMID 34960790, 2021). "Single-cell RNA-sequencing (scRNA-seq) of lung tissues from a COVID-19 autopsy case (Case 17) within 2 h after death revealed the presence of CD14+ monocytes (CD14+ Mono-1, -2), monocyte-derived alveolar macrophages (MoAM-1, -2), and other cell types." (PMID 34135479, 2021). "In conclusion, we observed a high frequency of immunosuppressive CD14+HLA-DRlo/neg MDSCs in COVID-19 patients, particularly ICU patients." (PMID 33640878, 2021). "In summary, circulating monocytes from acute COVID-19 patients, as examined at hospital arrival, were mostly classical CD14+CD16− monocytes with significant downregulation of HLA-DR and increased capacity to secrete pro-inflammatory cytokines." (PMID 34572439, 2021). "The onset of symptoms in COVID-19 is accompanied by a rapid increase in “classical” CD14+CD16– monocytes expressing the sialic acid-binding immunoglobulin-like lectin CD169/Siglec-1." (PMID 34239884, 2021). "This is consistent with previous studies that CD14+ monocytes from severe COVID-19 patients exhibited signature of immature monocytes, namely, downregulation of MHC II genes and upregulation of alarmin genes." (PMID 35095917, 2021). "We aimed to evaluate the changes of frequency of CD14+HLA-DRlo/neg MDSCs, a population of cells with potent immunosuppressive capacity, in COVID-19 patients." (PMID 33640878, 2021). "Impaired antigen presentation by CD14+ monocytes in COVID-19 has previously been suggested, mediated by IL-65." (PMID 34226537, 2021). "Adult COVID-19 patients had significantly lower CD14+ monocytes (p = 0.032) than age-matched and gender-matched healthy adults." (PMID 34976886, 2021). "We further characterized the transcriptomic changes of CD14+ monocyte from different subsets of COVID-19 patients." (PMID 35095917, 2021). "CD14+HLA-DRlow monocytes are expanded in severe COVID-19 patients, a likely consequence of the pervasive emergency myelopoiesis triggered by SARS-Cov2 infection." (PMID 33674591, 2021). "In the periphery, the authors reported enrichment of megakaryocytes and CD14+ monocytes during the progression stage of patients with severe COVID-19." (PMID 33863870, 2021). "In vitro studies showed that MAIT cell IFN-γ and granzyme B production were impaired by coculture with CD14+ cells from patients with severe COVID-19 and this is mediated by monocyte-derived IL-10 and IFN-α." (PMID 35381137, 2021). "Investigation into SPP1 mechanisms of action revealed that it drives proinflammatory activation of CD14+ monocytes and development of PD-L1+ neutrophils, both hallmarks of severe COVID-19." (PMID 34143756, 2021). "We analyzed the relationship between frequencies of CD14+HLA-DRlo/neg MDSCs and viral RNA loads, and the results indicated patients with COVID-19 with more severe disease requiring ICU admission had high viral RNA loads when compared to non-ICU patients." (PMID 33640878, 2021). "We next generated CD14+ cells from HSPCs in vitro using plasma from patients with mild (CVD1) or severe (CVD4) COVID-19." (PMID 34103408, 2021).
COVID-19 (continued). "In infection models by other RNA viruses such as influenza virus, HIV, Zika virus, and COVID-19, the switch of CD14 expression was also observed." (PMID 34177915, 2021). "Specifically, along with CD68, the immunoproteasome-related genes PSMB8, TAP1, PSMB9, PSMB10, and calreticulin (CALR) were all found to be expressed in the CD14+/CD16+ subpopulation of cells during mild COVID-19." (PMID 34225749, 2021). "Peripheral CD14+HLA-DRlo/neg MDSC frequencies were markedly increased in COVID-19 patients compared to HCs (P<0.0001)." (PMID 33640878, 2021). "We observed a shift towards a more mature CD163+ CD14+ phenotype within the DC3 subset in acute COVID-19 correlating with disease severity and inflammatory markers." (PMID 34614036, 2021). "This subset was part of an appropriate inflammatory CD14+ monocytic response in mild disease, while a dysfunctional CD14+ myeloid compartment characterized by low HLA-DR expression was observed in severe COVID-19." (PMID 34113347, 2021). "As expected, the core MS1 gene S100A8 was the most significantly up-regulated gene in CD14+ cells generated from HSPCs using severe COVID-19 plasma." (PMID 34103408, 2021). "It is still unclear, however, if the CD163+ CD14+ phenotype of DC3 in the blood of COVID-19 patients contributes to or is a byproduct of the inflammatory response." (PMID 34614036, 2021). "This enacts altered receptor expression on CD14+ monocytes, leading ultimately to accumulation of CD14+ monocytes in patients with severe forms of COVID-19." (PMID 34943191, 2021). "In line with previous reports, we observed an expansion of intermediate CD14+CD16+ monocytes in COVID-19 patients." (PMID 33479167, 2021). "With the R-package monocle, we constructed a cell trajectory of PSMB8 expression in the CD14+/CD68+ subpopulation of bronchoalveolar cells from COVID-19 patients." (PMID 34225749, 2021). "It is consistent with a previous report indicating that in symptomatic COVID-19 patients the percentage of CD14+/HLA-DR+ monocytes increase in the PBMCs while the CD14lowCD16+ inflammatory monocytes decrease as they leave the bloodstream and homing tissues." (PMID 34194422, 2021). "The correlations between CD14+HLA-DRlo/neg MDSCs frequencies and baseline clinical and laboratory indexes were determined and analyzed for COVID-19 patients." (PMID 33640878, 2021). "In vivo, a dramatic increase in IL-6-producing CD14+ /CD16+ monocytes was observed in the peripheral blood of COVID-19 patients in the intensive care unit." (PMID 34225749, 2021). "Regarding myeloid cells, the percentage of CD14+ monocytes in patients with severe COVID-19 was significantly higher than that in HC (P = 0.01)." (PMID 34349096, 2021). "A single cell study showed increased SIGLEC1 and VCAN in CD14+ monocytes from COVID-19 donors compared to healthy controls." (PMID 34108966, 2021). "We demonstrated GeneTrail’s capabilities by analyzing single-cell expression profiles of CD14 monocytes from COVID-19 patients and healthy controls." (PMID 34604304, 2021). "We saw a significant decrease of CD14+ monocytes in the mucosal and subepithelial region in COVID-19 patients compared to controls (cluster 3)." (PMID 34420043, 2021). "Compared with those in controls, the expression levels of genes involved in the innate immune defense were found diminished in CD14+ monocytes from COVID-19 patients." (PMID 35095917, 2021). "Bisque analysis of RNA-seq data of 207 COVID-19 patients also found that severe patients had higher CD14+/CD16+ monocyte ratios in the periphery at the early stage." (PMID 35095917, 2021). "Single-cell RNA sequencing of blood antigen-presenting cells in severe COVID-19 reveals that pathways related to NF-κB signaling were upregulated in plasmacytoid dendritic cells and CD14+ monocytes." (PMID 34817280, 2021).
COVID-19 (continued). "We obtained 18 data sets containing information on MDSCs and T cell subsets from COVID-19 patients, and the relationships between frequencies of CD14+HLA-DRlo/neg MDSCs and lymphocyte subsets were analyzed." (PMID 33640878, 2021). "In this study, we found that COVID-19 patients showed significant increases in the frequency of CD14+HLA-DRlo/neg MDSCs when compared to HCs, especially in patients admitted to ICU." (PMID 33640878, 2021). "Correlating with systemic inflammation and expansion of activated Tfh and B cells, DC3 from COVID-19 patients contained more CD163+ CD14+ cells." (PMID 34614036, 2021). "In previous studies, flow cytometric analyses of peripheral blood mononuclear cells from symptomatic patients with COVID-19 revealed the significant influx of CD14+ monocytes, consistent with our findings." (PMID 33424804, 2020). "We observed a significantly increased mean fluorescence intensity of phosphorylated BTK in CD14+ monocytes from patients with severe COVID-19 relative to that observed in healthy volunteers, an increase that was not due to differential levels of total BTK." (PMID 32503877, 2020). "Recent studies in humans have described an increase in the frequency of CD14 positive cells expressing low levels of HLA-DR in COVID-19 patients." (PMID 33247138, 2020). "In COVID-19 patients, we observed an expansion of intermediate CD14+CD16+ monocytes that tended to be highest in patients with a mild disease outcome." (PMID 32943497, 2020). "During the early recovery stage of COVID-19, an increase of CD14+ monocytes with inflammatory gene expression as well as abundance of CD14++IL-1β+ monocytes were recently described." (PMID 32695683, 2020). "Differentially expressed genes of CD14 + and CD16 + COVID-19 monocytes, especially in severe COVID-19 state, were associated with IFN responses, myeloid leukocyte activation, cytokine production and nuclear factor (NF)-κB signaling pathway." (PMID 33129318, 2020). "Likely, the same processes occur in patients with COVID-19 and, thus, IL-6 overproduction mediates low HLA-DR expression on CD14+ monocytes." (PMID 32722596, 2020). "During COVID-19, a decrease of classical monocytes (CD14+ and CD16−) was observed with an increase in intermediate (CD14+ and CD16−) and non-classical (CD14− and CD16+) monocytes." (PMID 32824753, 2020). "By contrast, a significantly higher percentage of CD14+CD16+ inflammatory monocytes existed in the peripheral blood of COVID-19 patients." (PMID 34676125, 2020). "Flow cytometric analysis of unstimulated whole blood samples revealed a significant increase in the percentage of IL-6+ CD14+ monocytes in patients with severe COVID-19 (n=4) compared with healthy volunteers (n=5)." (PMID 32503877, 2020). "It has also been reported that the CD14+CD16+ inflammatory intermediate monocyte percentage is higher in COVID-19 patients especially in those with more serious pulmonary complications compared to healthy individuals." (PMID 33375675, 2020). "The frequency of B cells after stimulation with the Spike 1 antigen was based on the classical biomarker, CD19, while previously excluding those expressing CD3, CD16, CD56, and CD14, as shown in the representative analysis strategy of a patient with acute COVID-19." (PMID 40006648, 2025). "In another study, the impact of SARS-CoV-2 infection on inflammatory bowel disease was analyzed by mining GEO RNA-sequencing and single-cell RNA-sequencing datasets, highlighting an increased proportion of CD14+ monocytes in COVID-19 patients and validating 38 hub genes related to CD14+ monocytes." (PMID 40149556, 2025). "We identified COVID-19-associated changes in the cellular composition of PBMCs in ESKD patients, including a decrease in the relative abundance of total monocytes and the subpopulations of CD14, CD16, and intermediate monocytes." (PMID 40532694, 2025).